TREX1 (three prime repair exonuclease 1)
Diseases named in the same sentence as TREX1 in open-access papers (continued):
Sharing a sentence is not in itself a finding about the gene and the disease.
diabetes (2 papers, 2024). "Following STZ treatment, Trex1−/− rats exhibited an earlier onset and higher incidence of diabetes, indicating the increased susceptibility to STZ-induced diabetes in Trex1−/− rats." (PMID 38166933, 2024). "We noticed that after onset of diabetes, lens of the Trex1−/− rats developed a cloudy and white appearance, resembling the manifestation of diabetic cataracts (DC) in human." (PMID 38166933, 2024). "To elucidate the role of TREX1 in spontaneous development of diabetes, we first examined the type of diabetes that Trex1−/− developed." (PMID 38166933, 2024). "We also found the levels of creatinine and urea in serum of Trex1−/− rats increased along time after onset of diabetes, suggesting the occurrence and progression of renal damage along disease course." (PMID 38166933, 2024). "We observed elevated levels of albuminuria, creatinine and urea in Trex1−/− rats after onset of diabetes, compared to those of WT rats." (PMID 38166933, 2024). "Further examination uncovered enhanced infiltration of CD68-positive macrophages in the renal tissues of diabetic Trex1−/− rats, supporting the conclusion that Trex1−/− rats develop diabetic nephropathy after onset of diabetes." (PMID 38166933, 2024). "Our data showed that Trex1−/− rats gradually developed cataract since the onset of diabetes, with mature cataract formation by 9 weeks after diagnosis." (PMID 38166933, 2024). "Trex1−/− rats also develop diabetic nephropathy and diabetic cataract after the onset of diabetes, which resembles the complications as diabetes patients." (PMID 38166933, 2024). "The prevalence of diabetes in Trex1−/− rats progressively increased with age, and approximately 70% of both male and female rats developed diabetes by 48 weeks of age." (PMID 38166933, 2024). "Furthermore, compared to WT rats, the lifespan of Trex1−/− rats was shortened after onset of diabetes." (PMID 38166933, 2024). "We speculate that the depletion of renal mtTFA and TREX1 in diabetes paved the way for DNA to stimulate the cGAS/STING pathway." (PMID 39589791, 2024). "Altered expression of mitochondrial transcription factor A, TREX1, and activity of the cGAS/STING pathway in diabetic kidneys." (PMID 39589791, 2024). "We next treated WT and Trex1−/− rats with a single low-dose STZ (30 mg/kg), a dose of which is insufficient to induce diabetes in WT rats." (PMID 38166933, 2024).
familial colorectal cancer type X (2 papers, 2022). Hereditary nonpolyposis colorectal cancer characterized by the absence of germline mutations in DNA mismatch-repair genes. "Recently, a potentially pathogenic TREX1 variant was found in a small cohort of familial colorectal cancer type X (FCCTX), although the functional consequences of the variant were not assessed." (PMID 35883600, 2022).
ischemia (2 papers, 2018 to 2024). A hypoperfusion of the BLOOD through an organ or tissue caused by a PATHOLOGIC CONSTRICTION or obstruction of its BLOOD VESSELS, or an absence of BLOOD CIRCULATION. "TREX1, primarily localized to white matter Iba1+ microglia associated with microvasculature adjacent to ischemic lesions, suggests a role for TREX1 in responding to ischemia." (PMID 39119967, 2024). "The increase of TREX1+ microglia in all regions of the brain in ischemic stroke compared to normal controls suggests that this is a general response to ischemia." (PMID 30062819, 2018). "A role for TREX1 in ischemia is further supported by our findings in the lesions of RVCL and ischemic stroke." (PMID 30062819, 2018).
ischemic stroke (2 papers, 2018 to 2023). A stroke disorder caused by obstruction of blood flow to the brain, due to thrombotic (local blood clot formation) or embolic (due to a blood clot or other material traveling from another site) event. "In ischemic stroke cases, these TREX1+ cells are observed in distinct tracts, usually within the adjoining white matter." (PMID 30062819, 2018). "The increase in TREX1 expression in ischemic stroke strongly indicates that it plays a role in the handling of necrotic debris." (PMID 30062819, 2018). "To determine if the differences noted between normal controls and RVCL were applicable to ischemic injury in general or were specific to RVCL, we also quantified the expression of TREX1 in sections consisting of undamaged brain tissue from cases with ischemic stroke." (PMID 30062819, 2018). "However, despite the increased expression of TREX1 in ischemic stroke, these cells represent less than 30% of microglia in all brain regions examined, with the exception of the basal ganglia (77.7 ± 6.8% of TREX1+ microglia)." (PMID 30062819, 2018).
prostate carcinoma (2 papers, 2025). A carcinoma that arises from epithelial cells of the prostate gland. "In alignment with these findings, our data reveal that TREX1 is overexpressed in prostate cancer tissues and exerts pro-tumorigenic effects in vitro." (PMID 41346575, 2025). "Notably, our analysis identified TREX1 as a critical determinant of poor clinical outcome; TREX1 is significantly overexpressed in prostate tumor tissues, and its knockdown markedly inhibits prostate cancer cell proliferation, migration, and invasion in vitro." (PMID 41346575, 2025). "We hypothesize that TREX1 functions as an “innate immune checkpoint” in prostate cancer by attenuating cGAS-STING signaling, thereby facilitating immune evasion and disease progression; nonetheless, this proposition warrants further experimental validation." (PMID 41346575, 2025). "Additionally, we investigated the expression levels of the model key gene TREX1 in prostate cancer tissues and assessed its functional implications in the proliferation, migration, and invasion of prostate cancer cells." (PMID 41346575, 2025). "If such activation occurs, the combination of TREX1 inhibition with immune checkpoint blockade may represent a promising strategy for prostate cancer immunotherapy." (PMID 41346575, 2025). "Differential expression of TREX1 in prostate cancer and adjacent normal tissues." (PMID 41346575, 2025). "Overall, this study establishes a novel prognostic signature for prostate cancer and elucidates the potential role of ICD/ferroptosis-related pathways, particularly the TREX1-mediated DNA sensing mechanism, in the progression of prostate cancer." (PMID 41346575, 2025). "Collectively, these findings indicate that TREX1, NOX4, and RRM2 may be significant contributors to the progression of prostate cancer; however, their precise roles and potential therapeutic implications warrant further investigation." (PMID 41346575, 2025). "Thirdly, while we provided functional evidence supporting the role of TREX1 in prostate cancer cells, we did not elucidate the molecular mechanisms through which TREX1 knockdown affects proliferation and invasion." (PMID 41346575, 2025).
sarcoidosis (2 papers, 2023 to 2026). Sarcoidosis is a multisystemic disorder of unknown cause characterized by the formation of immune granulomas in involved organs.
acute myeloid leukemia (1 paper, 2025). Acute myeloid leukemia (AML) is a group of neoplasms arising from precursor cells committed to the myeloid cell-line differentiation. "Most notably, ≥ 70% of the samples with TREX1 copy number increase in BLCA, CHOL (cholangiocarcinoma), DLBC (diffuse B-cell lymphoma), KICH, KIRP, LAML (acute myeloid leukemia), PAAD, and SKCM (skin cutaneous melanoma) also had 3p gain." (PMID 40581636, 2025).
Arthritis (1 paper, 2023). Inflammation of a joint. "Here authors show that cf DNA levels are higher in RA patients and that in a rat adjuvant-induced arthritis model, the exonuclease TREX1 suppresses synovial inflammation via promoting the degradation of cf DNA and inhibiting a senescence-like cellular state." (PMID 37474626, 2023). "With validation in conditional knockout rats via the Cre-LoxP system, the current study revealed that knockdown of the 3’–>5’ DNA exonuclease TREX1 increased the severity of arthritis in AIA rats." (PMID 37474626, 2023). "In contrast, similar to MTX-treated rats, AIA rats injected with AAV-TREX1 in either the knee joint cavity or tail vein showed significant decreases in the arthritis score and hind paw volume, suggesting that the severity of AIA was markedly attenuated in rats with overexpression of TREX1." (PMID 37474626, 2023). "Collectively, these findings indicate that TREX1 might play a suppressive role in the development of arthritis in AIA rats via the clearance of DNA fragments." (PMID 37474626, 2023). "Micro-CT analysis of hind paws further demonstrated the beneficial effects of TREX1 in AIA rats, and the protective effects on bone cartilage were consistent with the decreasing trends in the arthritis score and hind paw swelling in AIA rats with TREX1 overexpression." (PMID 37474626, 2023).
autoimmune myocarditis (1 paper, 2017). Autoimmune myocarditis is an autoimmune disease that affects the heart. "TREX1, which degrades cytosolic DNA, inhibits retrotransposition in vitro, and Trex1 knockout mice develop autoimmune myocarditis that is ameliorated by reverse transcriptase inhibitors." (PMID 28679751, 2017).
bone metastasis (1 paper, 2024). Transfer of a neoplasm from its primary site to bones. "And in the process of bone metastasis, TREX1 and RELA are protective factors, while CASP8 is a risk factor." (PMID 38835789, 2024).
central nervous system vasculitis (1 paper, 2018). Vasculitis affecting the blood vessels of the brain and/or spinal cord. "Another report of a 4-year-old girl with classic features of SLE and central nervous system vasculitis was found by whole exome sequencing to have a homozygous mutation in TREX1, implying that TREX1 might play a broader role in the pathogenesis of non-Mendelian SLE." (PMID 29922296, 2018).
cervical disease (1 paper, 2019). "Finally, we analyzed human cervical specimens and information from expression data series and showed that TREX1 expression steadily increases from cervicitis samples to CIN2, CIN3 and invasive squamous carcinoma samples." (PMID 30674977, 2019). "Our observations in cervical samples show that TREX1 upregulation may correlate with lesion progression during cervical disease." (PMID 30674977, 2019). "We observed that 25% of cervicitis samples were negative for TREX1 immunostaining (not shown)." (PMID 30674977, 2019).
cervical tumor (1 paper, 2019). "Furthermore, we provide the first evidence that TREX1 is essential for cervical tumor cells survival." (PMID 30674977, 2019). "Altogether, our results indicate that TREX1 upregulation is important for cervical tumor cells growth and may contribute with tumor establishment and progression." (PMID 30674977, 2019).
colorectal adenocarcinoma (1 paper, 2022). The most common type of colorectal carcinoma. "Midostaurin inhibited colorectal adenocarcinoma cell growth associated with the formation of dsDNA and ssDNA; the up-regulation of mRNA expression of cGAS, STING, IRF3, and IFNAR1; the down-regulation of Trex-1, c-Kit, and Flt3 protein expression." (PMID 36230769, 2022). "Midostaurin suppressed Flt3 and Trex-1 activation, and FLT3L activated both of these proteins in three colorectal adenocarcinoma cells." (PMID 36230769, 2022). "The protein expressions of Trex-1, c-KIT, and Flt3, but not PKCα/β/γ and VEGFR1, were down-regulated in midostaurin-treated colorectal adenocarcinoma cells and macrophages." (PMID 36230769, 2022).
congenital glaucoma (1 paper, 2022). "Although less discussed, besides the profound neurologic defects and presence of various autoantibodies, manifestations of congenital glaucoma, hepatic inflammation, endocrinopathies and susceptible to infections of Case 1 are also likely attributed to TREX1 mutation." (PMID 35964089, 2022).
cystic fibrosis (1 paper, 2020). Autosomal recessive disorder caused by pathogenic variants in the CFTR gene (cystic fibrosis transmembrane conductance regulator), which encodes a chloride and bicarbonate channel expressed in epithelial cells, and follow the diagnosis criteria. "Besides DNase II, and TREX1 (or DNase III), DNase I is the major serum endonuclease that degrades eDNA in the extracellular matrix, and been combined with antibiotics, or clinically applied to disperse P. aeruginosa biofilms in cystic fibrosis patients." (PMID 32244784, 2020).
diabetic nephropathy (1 paper, 2024). "In this study, we found that deficiency of Trex1 in rats leads to spontaneous development of T1D, accompanied by complications such as diabetic cataract and diabetic nephropathy." (PMID 38166933, 2024). "In summary, we found that Trex1 deficiency leads to spontaneous development of T1D in rats, accompanied by complications such as diabetic nephropathy and cataract." (PMID 38166933, 2024).
hereditary spastic paraplegia (1 paper, 2022). Hereditary spastic paraplegias (HSP) comprise a genetically and clinically heterogeneous group of neurodegenerative disorders characterized by progressive spasticity and hyperreflexia of the lower limbs. "These alterations were also observed in neuronal cells harboring a TREX1 mutation (V91M) that has been identified in hereditary spastic paraplegia (HSP) patients in Korea." (PMID 34997539, 2022).
Hereditary vascular retinopathy (1 paper, 2021). "Hereditary vascular retinopathy (HVR) is another rare disorder linked to mutations in TREX1 and eventually leads to blindness." (PMID 34503262, 2021).
Immunodeficiency (1 paper, 2022). Failure of the immune system to protect the body adequately from infection, due to the absence or insufficiency of some component process or substance. "Whereas SAVI mice exhibit inflammatory lung disease, T cell cytopenia, and immunodeficiency, TREX1-knockout animals develop lupus-like disease characterized by cardiac inflammation without lung disease." (PMID 36073546, 2022).
invasive carcinoma (1 paper, 2019). A carcinoma that is not confined to the epithelium, and has spread to the surrounding stroma. "On the other hand, CIN2/3 and invasive carcinoma samples displayed mainly strong cytoplasmic TREX1 staining throughout the lesion." (PMID 30674977, 2019).
lung disease (1 paper, 2022). "Thus, whereas TREX1 deficiency causes a type I interferonopathy in mice, STING gain of function results in a type II interferonopathy, at least with respect to lung disease and T cell phenotypes in mice." (PMID 36073546, 2022).
lupus erythematosus (1 paper, 2019). An autoimmune, connective tissue chronic inflammatory disorder affecting the skin, joints, kidneys, lungs, heart, and the peripheral blood cells. "Mutations in DNase III/TREX1 have also been associated with a familiar form of lupus erythematosus." (PMID 31440232, 2019).
neuroblastoma (1 paper, 2022). Neuroblastoma (NB) is the most common solid, extracranial childhood tumor. "To determine whether the loss of TREX1 affects neuronal development, we knocked down the TREX1 gene in SH-SY5Y neuroblastoma cells and examined neuronal differentiation by immunocytochemical analysis of neuron-specific markers, such as TUBB3, MAP2, and NF-L." (PMID 34997539, 2022).
ovarian serous adenocarcinoma (1 paper, 2025). An adenocarcinoma that arises from the ovary and is characterized by the presence of malignant epithelial cells that, in well differentiated tumors, resemble the epithelium of the fallopian tube or, in poorly differentiated tumors, show anaplastic features and marked nuclear atypia. "Co-occurrence of TREX1 gain with 3q gain was observed in ≥ 70% of CESC, CHOL, DLBC, KIRP, LAML, OV (ovarian serous adenocarcinoma), PAAD, and UCS samples, even though some of these tumor categories had very few TREX1 copy number gain events." (PMID 40581636, 2025).
pancreatic adenocarcinoma (1 paper, 2022). "Dong and collaborators detected TREX1 alterations in pancreatic adenocarcinomas and concluded that TREX1 might have a role in its carcinogenesis." (PMID 35181726, 2022).
pancreatic cancer (1 paper, 2016). "The result found that TREX1 gene could be applied as one of the important predictive factors for the overall survival rate of patients with pancreatic cancer." (PMID 27881153, 2016).
pancreatic ductal adenocarcinoma (1 paper, 2025). An infiltrating adenocarcinoma that arises from the epithelial cells of the pancreas. "For instance, increased TREX1 expression enables pancreatic ductal adenocarcinoma cells to evade immune detection by inhibiting the cGAS-STING pathway." (PMID 41346575, 2025).
Renal dysfunction (1 paper, 2021). "Renal dysfunction caused by thrombotic microangiopathy has been reported in a case with C-terminal frame-shift mutation in TREX1." (PMID 33482855, 2021).
renal fibrosis (1 paper, 2024). A final common manifestation of a wide variety of chronic kidney diseases characterized by glomerulosclerosis and tubulointerstitial fibrosis. "Thickening glomerular basement membrane (GBM), expansive mesangial matrix and renal fibrosis were observed in the kidney of diabetic Trex1−/− rats." (PMID 38166933, 2024).
squamous carcinomas (1 paper, 2019). "Finally, we observed an increase in TREX1 levels in precancerous lesions, squamous carcinomas and adenocarcinomas clinical samples." (PMID 30674977, 2019).
type 1 diabetes (1 paper, 2024). "In this study, we established a Trex1-deletion Sprague Dawley rat model, and unexpectedly, we found that the Trex1−/− rats spontaneously develop type 1 diabetes." (PMID 38166933, 2024).